SF3B1 (splicing factor 3b subunit 1)
Diseases named in the same sentence as SF3B1 in open-access papers (continued):
Sharing a sentence is not in itself a finding about the gene and the disease.
breast carcinoma (continued). "We validated that SF3B1neutral breast cancer cell lines (n = 7) express approximately twice as much SF3B1 mRNA as SF3B1loss cells (n = 5) by quantitative PCR (p<10−4)." (PMID 28177281, 2017). "Further analyses revealed that JA stabilizes endogenous SF3B1 protein and disrupts the binding of the protein to the nucleosome complex in breast cancer cells." (PMID 28198434, 2017). "Further analyses showed that JA stabilizes endogenous SF3B1 protein in breast cancer cells and induced dissociation of the protein from the nucleosome complex." (PMID 28198434, 2017). "Among breast cancer lines, we found increased SF3B1 protein expression in SF3B1neutral compared to SF3B1loss cells and SF3B1control-Cal51 vs. SF3B1Loss-Cal51 cells." (PMID 28177281, 2017). "We then calculated the correlation coefficient between splicing entropy of gene and SF3B1 expression across the eight breast cancer samples, and use those correlation coefficients as input for the iPAGE." (PMID 27272679, 2016). "Furthermore, a recent investigation demonstrated that suppressing the elevated levels of SF3B1 significantly decreased breast cancer cell proliferation, migration, and invasion." (PMID 38790189, 2024). "SF3B1 p.K700E mutations were prone to occurring in ER+/PR+/HER2- and early-stage breast cancers." (PMID 37760445, 2023). "In contrast to breast cancer, SF3B1 is less relevant and more splicing factors may be considered to reveal significant results." (PMID 36792691, 2023). "In support of the link between SF3B1 activity and AKT pathway, it has been recently reported that SF3B1K700E mutation can modulate the expression of key components of the AKT pathway with resulting increases in the migration/invasion of breast cancer cells." (PMID 35086552, 2022). "Interestingly, mutant SF3B1 has been shown to alter the abundance of proteins affecting metabolic pathways in breast cancer cells." (PMID 35565242, 2022). "Overexpression of SF3B1 and SF3B3 are associated with tamoxifen and fulvestrant resistance, and inhibition of another splicing factors, such as ZRANB2 and SYF2, reduces resistance to doxorubicin in breast cancer cells." (PMID 34439272, 2021). "Moreover, a recent study revealed that knock down of overexpressed SF3B1 expression reduced breast cancer cell proliferation, migration, and invasion." (PMID 33040078, 2020). "Besides, overexpression of SF3B1 has also been reported to drive tumorigenesis in several cancers, including breast cancer, prostate cancer, and myelodysplastic syndromes." (PMID 33040078, 2020). "Regarding expressions of SF3b complex components, it was reported that SF3B1 and SF3B3 are upregulated in fulvestrant/tamoxifen-resistant breast cancer cells, and SF3B3 overexpression associates with poor relapse-free and overall survival in ER-positive breast cancer patients." (PMID 32106418, 2020). "For instance, MYC addicted TNBCs cells have been shown to impart a specific dependency on the spliceosome via BUD31 and SF3B1 and impaired tumourigenesis was observed when SF3B1 was knocked down or pharmacologically inhibited in breast cancer cells MYC hyperactivation." (PMID 29848666, 2018). "SF3B1 K700E mutations were also found to associate with losses of 16q11-q13 and gains of 16q12-q13 indicating a distinct mechanism of breast cancer progression independent of the canonical early event of 1q gain and 16q loss." (PMID 29848666, 2018). "SF3B1 mutations were a poor prognostic factor in luminal B and progesterone receptor (PR)-negative breast cancer (P < 0.01)." (PMID 29383138, 2017). "Kaplan-Meier survival analysis showed that the SF3B1 mutation was not an independent predictor for OS in breast cancer patients overall (log-rank test: P = 0.385)." (PMID 29383138, 2017). "Moreover, SF3B1 hotspot mutations on codons K700, K666 and H662 have been described to induce dysregulation of metabolic enzymes, including PHGDH, in acute myeloid leukemia and breast cancer cells, leading to increased dependency on serine." (PMID 35565242, 2022).
breast carcinoma (continued). "Since SF3B1 was one of the nine splicing candidates for which depletion strongly inhibited cell proliferation in TNBC we evaluated whether PB could effectively inhibit proliferation of breast cancer cells." (PMID 33648524, 2021). "SF3B1 mutations have an incidence of approximately 20% in UM, 42% in mucosal melanoma (60% in anorectal melanoma and 44% in vulvovaginal melanoma), 7% in MDS (80% in refractory anemia with ring sideroblasts (RARS)-MDS, a subset of MDS), 10% in CLL and approximately 1.8% in breast cancer." (PMID 33333932, 2020). "Similarly, analysis of copy number alterations from 1042 cancer cell lines in the CCLE indicated 24% of cell lines harbor partial SF3B1 deletion, including 16/61 (26%) of breast cancer cell lines, but never homozygous loss (0/1042 cell lines)." (PMID 28177281, 2017). "Using a pooled-genome wide shRNA library screen and global proteomic profiling, we demonstrated that jerantinine A (JA) targets the cancer spliceosome through the upregulation of SF3B1 and SF3B3 proteins in breast cancer cells." (PMID 28198434, 2017). "Using a combined pooled-genome wide shRNA library screen and global proteomic profiling, we showed that JA targets the spliceosome by up-regulating SF3B1 and SF3B3 protein in breast cancer cells." (PMID 28198434, 2017). "Indeed, several splice factors including BUD31, SF3B1 and SRSF1 are known to be gene targets of the oncoprotein MYC and inhibition or knockdown of those in MYC hyperactivated breast cancer cells impairs tumorigenesis." (PMID 31666932, 2019). "Finally, pharmacological inhibition of the core spliceosome component SF3B1 reduced the tumorigenic and metastatic potential of MYC-driven human breast cancer cell lines." (PMID 26490253, 2015). "In contrast to SF3B1 mutant unselected breast cancers, no papillary carcinomas in this series were found to harbour AKT1 hotspot mutations." (PMID 25424858, 2015). "Interestingly, SF3B1 mutations correlate with good prognosis in MDS and UVM patients, while a reduced overall survival was observed in CLL and luminal B and progesterone receptor-negative breast cancer patients." (PMID 35053445, 2022). "However, direct evidence linking RIMS1, IK, SF3B1, and CBR1 genes specifically to lactylation modifications in breast cancer is lacking." (PMID 40406140, 2025).
melanoma (48 papers, 2015 to 2026). A malignant, usually aggressive tumor composed of atypical, neoplastic melanocytes. "Among the clonal SNVs, we observe hotspot coding mutations, such as Kras (G12D) and Gnaq (Q209L) that are well-known cancer drivers, and variants in Sf3b1 and Tfap2a, which are frequently mutated genes in melanoma." (PMID 40950124, 2025). "In this study, we analyzed the prognostic role of NRAS, KIT, BRAF, IGF2R and SF3B1 mutations in a series of mucosal melanomas." (PMID 34571863, 2021). "The occurrence of SF3B1 mutations in mucosal melanoma other than CM is higher, with a prevalence of 42% and hotspot mutations in 30–37%." (PMID 34071371, 2021). "Concomitant KIT/SF3B1 mutations in sun-protected cases suggest a common tumorigenic process with genital and anorectal mucosal melanomas." (PMID 34359736, 2021). "Comparison of mutational profiles of upper versus lower body sites mucosal melanomas found SF3B1 hotspot mutations in 27% of lower body (most commonly vulvar ad anorectal primary melanomas) compared to 6% in the upper body sites." (PMID 35008570, 2021). "Although R625 SF3B1 mutations are very rare in most melanoma, they have been identified in UM, including iris melanoma, and are less frequent in cutaneous melanoma as well as in vulvovaginal mucosal melanoma." (PMID 34071371, 2021). "The most frequent mutations seen in mucosal melanomas were in SF3B1 (27%), KIT (18%), and NF1 (17%)." (PMID 33724703, 2021). "A higher percentage of SF3B1 mutations was observed in patients with melanoma of anal/rectal origin when compared with patients with vulvovaginal or nasopharynx melanoma." (PMID 33724703, 2021). "For example, SF3B1 hotspot mutations are common in anorectal and vulvovaginal melanomas but are rare in mucosal melanomas from other sites and BRAF mutations are less common in the nasal cavity." (PMID 31320640, 2019). "The only other SF3B1 mutation was a p.C1123Y mutation that occurred in a conjunctival mucosal melanoma." (PMID 30847022, 2019). "SF3B1 mutations were also mostly in mucosal melanomas of European ancestry (7/8) and all were from primary tumor samples." (PMID 31320640, 2019). "In our cohort of 27 mucosal melanoma patients, six (22%) carried a SF3B1 mutation (in exons 14 and 23)." (PMID 30847022, 2019). "Analysis of the five B-box motifs in the human REPAG 3′ SS showed that the CTGAC motif is most significantly enriched over the genome background (p = 8E-18), similar to that in the aberrant 3′ SS in the SF3B1-mutated melanoma." (PMID 30693020, 2018). "In uveal and blue-nevus melanomas, mutations in the SF3B1 splicing factor arise recurrently; in carcinomas and gliomas, the regulator SRPK1 is overexpressed." (PMID 28653984, 2017). "The co-occurrence of an NRAS and an SF3B1 mutation in the CNS melanoma of the neurocutaneous melanocytosis patient in our study is interesting in this respect as the SF3B1 mutation was absent in the congenital melanocytic nevus of this patient." (PMID 26769193, 2016). "Among these, SF3B1 is the most frequently mutated, yet its hotspot mutations exhibit lineage specificity, with SF3B1R625 mutations predominantly found in melanoma and SF3B1K700E in hematologic malignancies." (PMID 42066087, 2026). "We detected clonal mutations of all types that affected genes known to contribute to melanoma initiation, including hotspot SNVs in Kras and Gnaq, SNVs in frequently mutated sites of Sf3b1 and Tfap2a, homozygous deletion of Cdkn2a, and amplifications of Met, Braf, Mitf, Kras, Cdk4, and Erbb3." (PMID 40950124, 2025).
melanoma (continued). "We further compared mucosal melanoma from patients of European and Asian ancestry (n = 48 and 42) and found that SF3B1 mutations were predominately observed in the former (22.9% vs. 2.4%), while SKP2 amplifications were more frequent in the latter (4.2% vs. 19%)." (PMID 35706047, 2022). "Interestingly, all these cases were sun-protected mucosal melanomas with high incidence of these KIT/SF3B1 co-mutations in ~20–40% of anorectal melanomas and ~33% of vulvar or genitourinary melanomas." (PMID 34359736, 2021). "Polymerase Chain Reaction (PCR) and Sanger sequencing techniques were performed to identify the mutational status of BRAF, NRAS, KRAS, NF1, KIT, PDGFRA and SF3B1 on 19 melanomas of the female genital tract, paired with 25 cutaneous melanomas, 18 acral melanomas and 11 melanomas of nasal cavity." (PMID 34102999, 2021). "Elucidating the impact of SF3B1 mutation in mucosal melanomas may provide more understanding of its role in tumorigenesis, and facilitate the development of new drugs (i.e. SF3B1 inhibitors) for mucosal melanomas with SF3B1 mutations." (PMID 30847022, 2019). "Melanomas with SF3B1 mutations had a similar mitotic rate when compared to non-SF3B1 mutated cases (15.6±4.4 vs 15.5±2.54 mitoses/mm2) but were more often ulcerated (SF3B1: 6 out of 6 cases vs non-SF3B1: 10 of 16 cases with ulceration data), and were comprised of heterogeneous cell types." (PMID 30847022, 2019). "Interestingly, recurrent mutations in the splicing factor SF3B1 have been identified in certain types of melanoma." (PMID 25977731, 2015). "A study of whole-genome sequences from cutaneous, acral, and mucosal subtypes of melanoma in 183 melanoma samples found that BRAF, NRAS, and NF1 were significantly mutated genes in AM, while SF3B1 (splicing factor 3B subunit 1) was identified in MM." (PMID 38469235, 2024). "Histological and molecular genetic analyses revealed an epithelioid-cell-type melanoma with complete circumferential involvement of the ciliary body and, so far, unreported GNAQ and SF3B1 mutations in ring melanoma." (PMID 35692773, 2022). "The overall frequency of main mutations in mucosal melanomas is as follows: NRAS (8%), BRAF (6%), neurofibromin 1 (NF1) (14%), KIT (13%), splicing factor 3b subunit 1(SF3B1) (15%)." (PMID 35008570, 2021). "Recently, BAP1 or SF3B1 mutations have been found to occur alongside GNAQ and GNA11 in approximately 20% of cases of unequivocally malignant blue nevus-like melanoma, suggesting that this is a late mutational event." (PMID 31861163, 2019). "The intermediate risk‐group melanomas had either BAP1 (4/13, 30.7%) or SF3B1 (5/13, 38.5%) mutations." (PMID 31025552, 2019). "We found that SF3B1 and KIT mutations predominantly occurred in melanomas originating in vulval/vaginal sites." (PMID 30847022, 2019). "In this study, we sought to determine the prevalence of genetic alterations in SF3B1 and of common oncogenic driver genes in mucosal melanomas, and investigate their impact on clinicopathologic characteristics and patient outcomes." (PMID 30847022, 2019). "In this study, we examined POM for alterations in candidate melanoma driver genes (BRAF, NRAS, KRAS, GNA11, GNAQ) and genes implicated in UM prognosis (EIF1AX, SF3B1, BAP1)." (PMID 30558566, 2018). "MLPA was conducted to detect chromosomal alterations and Sanger sequencing used to identify point mutations in candidate melanoma driver genes (BRAF, NRAS, KRAS, GNA11, GNAQ), and other genes implicated in melanoma prognosis (EIF1AX, SF3B1)." (PMID 30558566, 2018). "Mutations of SF3B1 of the U2 snRNP complex and U2AF35 cause aberrant 3′ splice site usage in leukemia, melanoma, breast and lung cancers." (PMID 30693020, 2018).
melanoma (continued). "It is thought that mutations in SF3B1 arise as a second genetic change in UM and blue nevus-like melanoma, after initial mutation in GNAQ or GNA11; however, SF3B1 changes can be driver mutations in MDS." (PMID 30558566, 2018). "These melanoma-private mutations occurred in genes linked to chromatin regulation (ARID1A and ARID2), cell growth (e.g., PIK3CA), cell adhesion (e.g., EPHA2), splicing (SF3B1), angiogenesis (PTPRB), and classic tumor suppressors (NOTCH3, CDKN2A, and PTEN)." (PMID 41516405, 2026). "Together, these observations suggest that co‐induction of BAP1 deficiency and SF3B1 mutation suppresses melanoma cell growth independent of the GNAQ/11 mutation status." (PMID 34706158, 2022). "A subset of acral and mucosal melanomas may have KIT mutations, in addition to gene amplifications and structural rearrangements, most frequently of the CCND1 gene and SF3B1." (PMID 34571969, 2021). "The presence of driver mutations such as BAP1 and SF3B1 has been shown to be strongly associated with metastasis and melanoma-specific mortality independent of GEP class." (PMID 34209210, 2021). "SF3B1, a mutation of codon 625 seen in 84% of the cases, does not correlate with prognosis in our series of mucosal melanomas." (PMID 34571863, 2021). "Different oncogenic drivers may be found in various subtypes of melanoma with neurofibromin prominent in acral melanoma and SF3B1 prominent in mucosal melanoma." (PMID 31466283, 2019). "Both SF3B1 (50%) and KIT (67%) mutations were most frequently mutated in tumors of female genital origin and anorectal region (33.3% for SF3B1 and KIT) compared to a single SF3B1 mutant conjunctival melanoma in the upper body sites." (PMID 30847022, 2019). "In contrast, the SF3B1 mutation (c.1874G > A (p.(Arg625His))) was present in the CNS melanoma but not in the melanocytic nevus." (PMID 26769193, 2016). "Although not emphasized in previous publications, some mucosal melanomas may carry concomitant KIT/SF3B1 mutations." (PMID 34359736, 2021). "For the melanoma patient with two tumor sites, three tier-1 genes, namely PSIP1, RSPO2, and SF3B1, were identified in both tumor tissues and ctDNA." (PMID 37878600, 2023). "Changes affecting many other genes are also common, particularly in advanced melanoma, including ARID2, RAC1, and SF3B1, amongst many others." (PMID 31861163, 2019). "Furthermore, besides SF3B1 and KIT mutations, other variants have been described in the context of mucosal melanoma, including amplifications of CCND1, MDM2 and KRAS, however this was not assessed this cohort and could represent a source of additional driver eventsin this cohort." (PMID 30847022, 2019). "In a word, compared with gynecologic melanoma, non-gynecologic melanoma harbored distinct mutation rates in KIT, BRAF, SF3B1, KRAS and NRAS genes." (PMID 34102999, 2021). "We observed that gynecologic melanoma harbored distinct mutation rates in c-KIT, BRAF, SF3B1, KRAS and NRAS genes compared with non-gynecologic melanoma." (PMID 34102999, 2021). "However, equine melanomas from mucosal‐like or mucocutaneous sites showed a landscape of driver genes that was less populated than human mucosal melanoma, and there were fewer recurrently mutated genes in common with human mucosal melanoma, with no mutations found in SF3B1, ATRX or NF1." (PMID 32652526, 2020). "However, none of the cases were found to harbor SF3B1 and KIT mutations in cutaneous melanomas, acral melanomas and melanomas of nasal cavity." (PMID 34102999, 2021).
melanoma (continued). "Non-CSD-associated melanomas encompass acral and mucosal melanomas that usually do not show BRAF, NRAS, or NF1 mutations (triple wild-type), but in a subset may have KIT or SF3B1 mutations." (PMID 34571969, 2021). "Notably, none of the cases were found to harbor SF3B1, NF1, KIT and PDGFRA mutations in cutaneous melanomas, acral melanomas and melanomas of nasal cavity." (PMID 34102999, 2021). "Moreover, this location of the melanoma is an entirely distinct entity from skin melanoma and melanomas of the nasal cavity, while cervix melanomas also have some particularities, and do not suffer recurrent KIT mutations, or mutations of the NRAS and SF3B1 genes." (PMID 34209084, 2021). "In addition (and like SF3B1 mutations), the EIF1AX mutations in our cases occurred both in melanocytomas as well as melanomas, suggesting that they are not necessarily associated with worrisome histology, but the prognostic implications of these mutations remain to be elucidated." (PMID 26769193, 2016). "Eight other cases carried one or more mutations in genes also found in uveal or mucosal melanoma, but not in cutaneous melanoma: BAP1, SF3B1, or EIF1AX and hence were similarly suspect as misclassified." (PMID 34939927, 2021). "Notably, the canine oral melanomas in our series also lacked SF3B1 and GNAQ mutations, and no mutations in POLE, PTPRD, or DMXL2 were found, suggesting that these canine cancers may not represent a faithful genetic model for the subset of human mucosal melanomas with mutations in these genes." (PMID 30664638, 2019).